JAK1 (Janus kinase 1)
Diseases named in the same sentence as JAK1 in open-access papers (continued):
Sharing a sentence is not in itself a finding about the gene and the disease.
myelofibrosis (137 papers, 2012 to 2026). A partial or complete replacement of the bone marrow stroma by fibrous tissue. "Ruxolitinib (RUX), a JAK1/2 inhibitor, demonstrated treatment benefits for myelofibrosis (MF) in intermediate-1 (Int-1)-risk patients with a significant disease burden; however, the evidence is scarce." (PMID 41877599, 2026). "Ruxolitinib, a JAK1/2 inhibitor, is associated with improved splenomegaly and myelofibrosis-associated symptoms." (PMID 39110143, 2024). "Management strategies for PMF have evolved over the last two decades, including approval of ruxolitinib as the first Janus kinase 1 (JAK1)/JAK2 inhibitor for patients with intermediate or high-risk myelofibrosis." (PMID 36641455, 2023). "Ruxolitinib (ruxo) is a potent JAK1/2 inhibitor used for the treatment of high-risk myelofibrosis and Fedratinib (fed) is a JAK2 specific inhibitor currently in Phase III trials for high-risk myelofibrosis." (PMID 31817106, 2019). "To explore this option in UBC, we used RX, a potent JAK1/JAK2 inhibitor approved for the treatment of intermediate/high risk myelofibrosis." (PMID 31438567, 2019). "Ruxolitinib is a JAK1/2 inhibitor that is approved for the treatment of myelofibrosis and polycythemia vera in JAK2 gain of function mutations." (PMID 31636267, 2019). "The oral Janus associated kinase (JAK1/2) inhibitor ruxolitinib has been available for treatment of patients with intermediate or high-risk myelofibrosis in Europe since 2012." (PMID 30043249, 2018). "Ruxolitinib, a JAK1/2 inhibitor, is used for the treatment of intermediate or high-risk myelofibrosis." (PMID 30040819, 2018). "The randomized, double-blind, placebo-controlled, phase 3 COMFORT-I trial evaluated the JAK1/JAK2 inhibitor ruxolitinib in patients with intermediate-2/high-risk myelofibrosis." (PMID 28228106, 2017). "Ruxolitinib is a selective oral JAK1/2 inhibitor approved for the treatment of patients with intermediate-2 or high-risk primary myelofibrosis." (PMID 27502249, 2016). "Ruxolitinib, a JAK1/2 inhibitor approved for intermediate-2/high-risk myelofibrosis, was recently employed in SR-GvHD with encouraging overall response rates." (PMID 27502249, 2016). "The same effects were observed with ruxolitinib, a more specific JAK1/2 inhibitor that has been approved by the FDA for patients with intermediate- to high-risk myelofibrosis." (PMID 25149535, 2014). "Ruxolitinib was the first JAK1/2 inhibitor that has been approved for the treatment of intermediate or high-risk myelofibrosis, including primary myelofibrosis, post-polycythemia vera myelofibrosis, and post-essential thrombocythemia myelofibrosis." (PMID 32086626, 2020). "Interestingly, JAK1/2 inhibitor treatment was associated with an increased risk of progression to aggressive lymphomas in patients with myelofibrosis who have a preexisting B cell clone in their bone marrow." (PMID 31684088, 2019). "Ruxolitinib, a Janus kinase 1 and 2 inhibitor, demonstrated improvements in spleen volume, symptoms, and survival over placebo and best available therapy in intermediate-2 or high-risk myelofibrosis patients with baseline platelet counts ≥100 × 109/L in phase III studies." (PMID 24283202, 2013). "Momelotinib, a novel JAK1/2 inhibitor with inhibitory activities on activin A receptor type I, has shown breakthrough clinical efficacy in patients with myelofibrosis (MF) and anemia, a disease‐related manifestation of challenging management." (PMID 40955124, 2026). "Ruxolitinib, the first JAK1/2 inhibitor licensed for the treatment of myelofibrosis, was shown to reduce spleen size and alleviate constitutional symptoms." (PMID 40699626, 2025). "The successful treatment of iMCD-TAFRO with ruxolitinib (a potent and preferential JAK1/2 inhibitor approved for the treatment of myelofibrosis) has been reported." (PMID 39944226, 2025).
myelofibrosis (continued). "In clinical trial NCT02493530, the combination of umbralisib and ruxolitinib (a JAK1/2 inhibitor) attained an ORR of 56.5% in ruxolitinib-resistant myelofibrosis patients, including two cases of complete remissions." (PMID 41568384, 2025). "Ruxolitinib, a JAK1 inhibitor, is approved for the treatment of myelofibrosis and acute graft-versus-host disease and has been demonstrated to regulate the immune microenvironment by inhibiting myeloproliferation." (PMID 40949126, 2025). "Since its FDA approval in 2011 for the treatment of myelofibrosis, the clinical use of ruxolitinib as a selective JAK1 and JAK2 inhibitor has greatly expanded." (PMID 40117367, 2025). "The newest JAK1/JAK2 inhibitor, momelotinib (CYT387), has been studied for the treatment of intermediate- to high-risk primary and secondary myelofibrosis (MF)." (PMID 40699626, 2025). "The JAK1/2 inhibitor (JAKi), ruxolitinib, has demonstrated efficacy in reducing splenic size, alleviating myelofibrosis-related symptoms, and improving overall survival." (PMID 38646256, 2024). "The JAK1/2-selective inhibitor Ruxolitinib has received FDA approval for treating myelofibrosis, polycythemia vera, graft versus host disease, atopic dermatitis, and vitiligo." (PMID 38805119, 2024). "CYT387, a drug for the treatment of myelofibrosis, can inhibit interferon and interferon-stimulated gene expression through JAK1/JAK2 (kinases mediating IFN signaling) and TBK1/IKKε (kinases mediating RLR and TLR signaling) pathways." (PMID 39738014, 2024). "Ruxolitinib (RUX), an oral JAK inhibitor approved by the FDA for the treatment of myelofibrosis, polycythemia vera, and graft versus host disease works through reducing the abundance of cytokines and growth factor receptors that utilize JAK1 and JAK2." (PMID 38319731, 2024). "Ruxolitinib is an orally bioavailable JAK1/2 inhibitor, approved by the FDA for intermediate or high‐risk myelofibrosis and used in the setting of graft‐vs‐host disease and post‐MPN AML." (PMID 38662349, 2024). "Weight gain is a known adverse effect of ruxolitinib, a JAK1/2 inhibitor that is the mainstay of treatment for many patients with myelofibrosis." (PMID 37455900, 2023). "Ruxolitinib was the first JAK1/2 inhibitor approved for the treatment of patients with myelofibrosis (MF) with splenomegaly and/or symptoms." (PMID 37894394, 2023). "Ruxolitinib (RUX) is a Janus kinase 1/2 inhibitor (JAKi) approved in the EU for treating disease‐related splenomegaly or symptoms in adults patients with myelofibrosis (MF)." (PMID 37792065, 2023). "Most patients with myelofibrosis (MF) discontinue ruxolitinib (JAK1/JAK2 inhibitor) in the first 5 years of therapy due to therapy failure." (PMID 37894394, 2023). "Ruxolitinib is a dual JAK1/2 specific inhibitor and has been approved by the FDA for the treatment of intermediate and high-risk myelofibrosis." (PMID 35145818, 2022). "Ruxolitinib (Novartis) is another approved inhibitor for the treatment of myelofibrosis, which targets both JAK1 and JAK2 and is currently being used in a number of clinical studies (phase I, II, and III) in solid tumors including BC." (PMID 35401182, 2022). "The development and approval of ruxolitinib, the first JAK1/2 inhibitor indicated to treat myelofibrosis, has improved patient outcomes, with higher spleen and symptoms responses, improved quality of life, and overall survival." (PMID 35877255, 2022). "Ruxolitinib is a selective JAK1/2 inhibitor that was originally approved by the FDA for the treatment of myelofibrosis and polycythemia vera." (PMID 35897741, 2022). "Ruxolitinib, a JAK1/JAK2 inhibitor, is approved by the FDA for patients with intermediate- and high-risk myelofibrosis." (PMID 35773269, 2022). "Ruxolitinib is a specific JAK1/2 inhibitor approved for treating myelofibrosis and for steroid-refractory acute and chronic graft-versus-host disease (SR-GvHD)." (PMID 36685552, 2022).
myelofibrosis (continued). "Treatment of myelofibrosis with ruxolitinib is an example of precision medicine, since this drug is a selective inhibitor of JAK1 and JAK2." (PMID 35337171, 2022). "Several JAK inhibitors have entered clinical trials, including ruxolitinib, the first JAK1/2 inhibitor to become commercially available for the treatment of myelofibrosis and polycythemia vera." (PMID 34867980, 2021). "Examples of repurposed drugs are ruxolitinib and momelotinib, which are approved for myelofibrosis, targeting the JAK1/JAK2 gene pathway." (PMID 34721386, 2021). "Ruxolitinib, a potent Janus kinase 1/2 inhibitor, has demonstrated durable improvements in patients with myelofibrosis." (PMID 34224180, 2021). "Collectively, these human data suggest that point mutations in the pseudokinase domain of JAK1 are critical to pathological processes, similarly to the well-known JAK2 V617F mutation found in polycythaemia vera, myelofibrosis, and essential thrombocythemia." (PMID 35046931, 2021). "The JAK1/2 inhibitor, Ruxolitinib, is an approved drug for the treatment of polycythemia vera and myelofibrosis." (PMID 34359681, 2021). "JAK1/2 inhibitor ruxolitinib (RUX) is approved in patients with myelofibrosis but the impact of pretreatment with RUX on outcome after allogeneic hematopoietic stem cell transplantation (HSCT) remains to be determined." (PMID 34023851, 2021). "The specific JAK1/2 inhibitor--ruxolitinib is used to treat myelofibrosis and has been approved by FDA." (PMID 32169038, 2020). "In this Phase III, randomized, placebo-controlled study, patients in the experimental group will be given ruxolitinib – a JAK1/2 inhibitor approved to treat myelofibrosis, among other diseases – in addition to standard of care therapy." (PMID 33230423, 2020). "The pan-PIM kinase inhibitor, PIM447, is being tested in combination with Ruxotilinib, a JAK1/2 inhibitor in myelofibrosis (NCT02370706)." (PMID 32042115, 2020). "Ruxolitinib, a JAK1/JAK2 tyrosine kinase inhibitor, is currently extensively employed in MPN-associated myelofibrosis therapy." (PMID 33114087, 2020). "Utilization of cancer therapies to treat CRS in patients diagnosed with COVID-19 offers promise, and there is currently a Phase III study underway using ruxolitinib, a JAK1/2 inhibitor used to treat myelofibrosis." (PMID 33230423, 2020). "Ruxolitinib, a JAK1/JAK2 tyrosine kinase inhibitor, is currently being extensively employed in MPN-associated myelofibrosis therapy, but it has little antioxidative capacity." (PMID 33114087, 2020). "Contemporary drug therapy of myelofibrosis centers on the use of the Janus kinase 1/2 (JAK1/2) inhibitor, ruxolitinib." (PMID 35309812, 2019). "Ruxolitinib, a JAK1/JAK2 inhibitor which is used for the treatment of myelofibrosis, received approval from multiple agencies due to its ability to reduce symptoms of the disease, including splenomegaly by 35%." (PMID 30956775, 2019). "Ruxolitinib is an oral selective Janus-associated kinase 1 (JAK1) and JAK2 inhibitor that was initially approved by the FDA in 2014 for treatment of myelofibrosis." (PMID 30519495, 2018). "In particular, myelofibrosis patients treated with the Jak1/2 inhibitor Ruxolitinib can gain up to 9.4 kg of weight after 1 year of therapy." (PMID 29867515, 2018). "Ruxolitinib is an FDA-approved small molecule inhibitor of JAK1/2 for the treatment of myelofibrosis and polycythemia vera; it has minimal significant side effects following short-term use in healthy individuals." (PMID 29778097, 2018). "Ruxolitinib is the first JAK1/JAK2 inhibitor specifically approved for the treatment of disease-related splenomegaly or symptoms in adult patients with primary myelofibrosis." (PMID 35620778, 2018). "We investigated the therapeutic potential of ruxolitinib, a JAK1/JAK2 inhibitor that has been FDA-approved for the treatment of myelofibrosis, to treat ovarian cancer either alone or in combination with conventional chemotherapy agents." (PMID 29849942, 2018).
myelofibrosis (continued). "Currently, ruxolitinib, a JAK1/2-targeting agent, is widely used for myelofibrosis and polycythemia vera and showed suppression of phosphorylated STAT3 in dose dependent manner." (PMID 29340087, 2017). "Preventing and reducing STAT5 activation through the use of JAK2 inhibitors proved clinical efficacy in patients with myelofibrosis and PV, and the first-in-class JAK1 and JAK2 inhibitor ruxolitinib was approved recently for selected categories of patients." (PMID 29228564, 2017). "We applied Ruxolitinib, a newly discovered inhibitor of JAK1/JAK2 previously used in the treatment of myelofibrosis." (PMID 28497028, 2017). "Ruxolitinib, a small molecule inhibitor of JAK1 and JAK2 kinases, has been approved by the FDA for the treatment of polycythemia vera and intermediate to high-risk myelofibrosis." (PMID 29082853, 2017). "A JAK1/2 inhibitor, ruxolitinib, has been approved by FDA for the treatment of patients with intermediate or high-risk myelofibrosis and polycythemia vera." (PMID 28410228, 2017). "Ruxolitinib, a JAK1 and JAK2 inhibitor drug, has recently been approved for the treatment of patients with high- or intermediate-risk myelofibrosis (MF) with symptomatic splenomegaly." (PMID 26316485, 2015). "Ruxolitinib, a JAK1 and JAK2 inhibitor drug, has recently been approved for the treatment of patients with high- or intermediate-risk myelofibrosis with symptomatic splenomegaly." (PMID 26316485, 2015). "In November 2011, the US Food and Drug Administration approved the use of the JAK1- and JAK2-selective inhibitor ruxolitinib for the treatment of patients with intermediate- or high-risk myelofibrosis." (PMID 26316489, 2015). "STAT3 is activated by JAK1–2, and the JAK1–2 inhibitor ruxolitinib has been approved by the FDA for the treatment of myelofibrosis and polycythemia vera, and is currently being tested in pancreatic and breast cancer clinical trials." (PMID 25762644, 2015). "CYT387 is an orally available, potent small molecule inhibitor of the JAK1/2 pathway currently undergoing Phase I/II clinical trials for the treatment of myelofibrosis, a frequently diagnosed fatal myeloproliferative disorder." (PMID 24782986, 2014). "Very recently, a CEL patient with PCM1-JAK2 was successfully treated with a JAK1/2 inhibitor ruxolitinib, a drug which hitherto showed modest activity against myelofibrosis with JAK2V617F." (PMID 23372669, 2013). "In November 2011, the US Food and Drug Administration approved the use of the JAK1- and JAK2-selective inhibitor ruxolitinib for the treatment of patients with intermediate or high-risk myelofibrosis, including PMF, post-PV MF, and post-ET MF." (PMID 22852872, 2012). "In contrast, FDA-approved Jak/Stat3 inhibitors like ruxolitinib, which target JAK1/2 and improve survival in myelofibrosis, may offer a safer alternative." (PMID 41158754, 2026). "Ruxolitinib (RUX) is a JAK1/2 inhibitor widely used in patients with myelofibrosis (MF)." (PMID 41743264, 2026). "Further insights into the interplay between JAK1 selectivity and infection risk are provided by real-life data on the employment of a novel JAK2-selective drug, fedratinib, used in the therapy of intermediate or high-risk, primary or secondary myelofibrosis." (PMID 39124690, 2024). "Ruxolitinib is a JAK1/2 inhibitor that has revolutionized the approach to myelofibrosis." (PMID 36675507, 2023). "For JAK/STAT mutations, the JAK1/2 inhibitors, ruxolitinib and momelotinib, have been investigated and are now FDA-approved for myelofibrosis, and researchers remain optimistic that their use in myelofibrosis can pave the way for ML-DS treatment as well." (PMID 37444375, 2023). "More extensive use of the JAK1/JAK2 inhibitor ruxolitinib is associated with a greater risk of mycobacterial infections (Mycobacterium tuberculosis and atypical mycobacterial infections) in the treatment of patients with myelofibrosis and polycythemia vera." (PMID 36159783, 2022).
myelofibrosis (continued). "Furthermore, the combination therapy with Jak1/2 inhibitor resulted in complete reversal of myelofibrosis and osteosclerosis." (PMID 36100613, 2022). "Ruxolitinib is one of the specific JAK1/JAK2 inhibitors approved by the FDA against myelofibrosis." (PMID 35401182, 2022). "Ruxolitinib is a selective JAK1 and JAK2 inhibitor that targets JAK/STAT-associated signaling, exhibiting an effective clinical treatment of myelofibrosis adopted by FDA, which was used to confirm the effect of ENC1 on activation of the JAK2/STAT5/AKT axis in CRC cells." (PMID 33816464, 2021). "Interestingly, two phase II clinical trials explored ruxolitinib, a JAK1-2 inhibitor approved for the treatment of primary myelofibrosis, in CLL." (PMID 31817171, 2019). "Recent data from an open-label study and a case report suggest that long-term therapy with the JAK1/2 inhibitor ruxolitinib may improve or stabilise the progression of BMF in a proportion of patients with myelofibrosis." (PMID 26357842, 2015). "The impact of JAK1/2 inhibition on symptom burden and splenomegaly in myelofibrosis is considered to be driven mainly by its pronounced anti-inflammatory efficacy as evidenced by a marked reduction in several proinflammatory cytokines during JAK-inhibition therapy." (PMID 26538833, 2015). "Ruxolitinib, an oral JAK1 and JAK2 inhibitor, is approved in the US for patients with intermediate or high-risk myelofibrosis (MF), a chronic neoplasm associated with aberrant myeloproliferation, progressive bone marrow fibrosis, splenomegaly, and burdensome symptoms." (PMID 24283870, 2013). "Furthermore, we found that especially Momelotinib its important role as a JAK1/JAK2/ACVR1 inhibitor in alleviating myelofibrosis and anti‐inflammation, which may serve as a potential drug for COPD treatment." (PMID 38578019, 2024). "Other drugs targeting the Jak/Stat pathway that have been developed more recently than the MIPE 4.0 drug library could also be investigated, such as Ruxolitenib—a JAK1/2 inhibitor that is FDA approved for the indication of myelofibrosis and topically for atopic dermatitis." (PMID 35741605, 2022). "Interestingly, we found that ruxolitinib, a specific JAK1/2 inhibitor which used for myelofibrosis treatment, could substantially reduce plasma IL-6, IL-1β, IFN-γ and TNF-α contents in atherosclerotic rabbits." (PMID 32169038, 2020). "Ruxolitinib is a potent JAK1/2 inhibitor, and the first therapeutic of this class to be approved by the U.S. Food and Drug Administration (FDA) for the treatment of intermediate or high-risk myelofibrosis, based on combined results of the COMFORT-I and COMFORT-II Trials." (PMID 31684088, 2019). "Ruxolitinib, a selective JAK1 and JAK2 inhibitor, is frequently used to treat polycythemia vera (PV), myelofibrosis, and graft-vs.-host disease (GVHD)." (PMID 41164159, 2025). "This case demonstrates the critical role of JAK1 and JAK2 gene transcription in antifungal defense, particularly in patients receiving ruxolitinib therapy, a JAK1 and JAK2 inhibitor, for PV or myelofibrosis." (PMID 41164159, 2025). "Ruxolitinib as JAK1 and selectivity of JAK2 inhibitors, has been the United States Food and Drug Administration (FDA) approved for the treatment of b myelofibrosis." (PMID 40271123, 2025). "The JAK1/2 inhibitor, ruxolitinib, is FDA-approved for the treatment of myelofibrosis and has been extensively tested in breast cancer patients." (PMID 39768178, 2024). "There are some JAK1 inhibitors used in clinics, such as Ruxolitinib, a selective inhibitor of JAK1 and JAK2, for the treatment of myelofibrosis and polycythemia." (PMID 37895906, 2023). "Combined JAK1/2 and SMAD3 treatment proved to be the most efficient in preventing the myelofibrosis induced by BM-MSCs via neoplastic MPN mononuclear cells regardless of the presence of JAK2 mutation." (PMID 35288649, 2022).